EGR3 (early growth response 3)
Diseases named in the same sentence as EGR3 in open-access papers (continued):
Sharing a sentence is not in itself a finding about the gene and the disease.
prostate carcinoma (14 papers, 2013 to 2025). A carcinoma that arises from epithelial cells of the prostate gland. "Downregulation of EGR3 has been identified as a risk factor for various types of cancer, including gastric and prostate cancers." (PMID 39213172, 2024). "The Egr3-correlated gene list noticeably clusters into several important functions associated with prostate cancer, such as immune response and proliferation." (PMID 23342084, 2013). "By performing this analysis on an independent dataset and a different Affymetrix platform, we have validated that our list of 80 genes is reproducibly associated with Egr3 expression in prostate cancer." (PMID 23342084, 2013). "Egr3-null mice do exist, and the result of crossing these mice with a prostate cancer model such as TRAMP or PTEN-deficient mice would be of great interest." (PMID 23342084, 2013). "Overexpression of the EGR3 gene is known to inhibit the growth of hepatocellular carcinoma, and is also associated with a better prognosis in patients with gastric cancer and prostate cancer." (PMID 40585280, 2025). "EGR3 loss was associated with prostate cancer progression and poor prognosis." (PMID 36032660, 2022). "In prostate cancer, EGR3 suppresses metastasis by inducing the expression of tumor suppressor genes, such as ZFP36 and SOCS3, while additional evidence suggests that EGR3 loss correlates with relapse and reduced survival." (PMID 40649712, 2025). "GADD45b was recently identified as an EGR3-dependent gene in prostate cancer, and EGR3 was shown to bind to the GADD45B promoter in vivo and upregulate expression of GADD45B in vitro." (PMID 35941129, 2022). "Other studies have discovered that the expression level of EGR3 mRNA in prostate cancer samples is high, which can be used as a marker for cancer diagnosis and as a prognostic indicator that distinguishes between invasive and noninvasive tumors." (PMID 31844579, 2019). "The Aperio ImageScope positive pixel count algorithm was also used to compare strong Egr3 staining in the normal and prostate cancer samples." (PMID 23342084, 2013). "Analysis of the normalized expression data from the 127 prostate samples revealed that Egr3 (probe set 206115_at) is significantly over-expressed in prostate cancer compared to normal prostate tissue." (PMID 23342084, 2013). "Here we report the over-expression of Egr3 mRNA and protein in prostate cancer compared to normal prostate tissue." (PMID 23342084, 2013). "The available prostate tissue immunohistochemistry images for Egr3 staining consist of 20 prostate cancer samples from 11 patients and 3 normal prostate samples from 3 donors." (PMID 23342084, 2013). "While the in-silico approach we used to examine Egr3 expression and possible target genes is very informative, much work remains to be done in order to determine Egr3 mode of action and target genes in prostate cancer." (PMID 23342084, 2013). "To provide biological validation of our findings, we achieved stable knockdown of Egr3 expression in M12 prostate cancer cells." (PMID 23342084, 2013). "Using the Human Protein Atlas, we also detail a unique in-silico method for investigating the over-expression of Egr3 protein in prostate cancer." (PMID 23342084, 2013). "In agreement with the SPECS data, we found that Egr3 protein is significantly increased in prostate cancer." (PMID 23342084, 2013). "Egr3 RNA and protein are expressed predominantly in the epithelial cells in both normal prostate glands and prostate cancer." (PMID 23342084, 2013). "We conclude that IL6 and IL8, identified as Egr3 potential target genes using in silico analysis, are indeed regulated by Egr3 in prostate cancer cells." (PMID 23342084, 2013). "Similarly, in hepatocellular carcinoma, canine mammary cancer, and prostate cancer, EGR3 appears to inhibit growth and metastasis, often through suppression of the epithelial–mesenchymal transition or induction of apoptosis-related pathways." (PMID 40649712, 2025).
prostate carcinoma (continued). "EGR3, in addition to its role in regulation of immune cell activation, was recently determined to be a critical metastasis suppressor in other cancers like prostate cancer." (PMID 37435088, 2023). "In prostate cancer cells, EGR3 blocked the EMT process and suppressed cell migration and invasion." (PMID 36032660, 2022). "EGR3 (early growth response 3) is a member of zinc finger transcription factors and may be regarded as a tumor suppressor in prostate cancer, gastric cancer, lung cancer, and leukemia." (PMID 34249704, 2021). "EGR3 expression, which is lower in aggressive prostate cancer, was also significantly decreased." (PMID 26019137, 2015). "A study showed that Egr3 exhibits nuclear localization in a prostate cancer cell line." (PMID 24722338, 2014). "Although Egr3 is up-regulated at the mRNA level, it may be the Egr3 protein level that is important to the function of Egr3 in prostate cancer." (PMID 23342084, 2013). "Because Egr3 is a transcription factor we sought to determine whether other transcripts were specifically elevated in correlation with the levels of Egr3 transcript in the prostate cancer tissues." (PMID 23342084, 2013). "The combined results indicate that Egr3 is a biomarker of poor outcome prostate cancer." (PMID 23342084, 2013). "Based on our knowledge of Egr1 and the common DNA binding characteristics of all EGR transcription factors, we hypothesize that Egr3 does indeed play a role in either the formation or progression of prostate cancer." (PMID 23342084, 2013). "The discovery of Egr3 regulation of these interleukins could potentially broaden our understanding of inflammation and the immune system in prostate cancer." (PMID 23342084, 2013). "Analysis of Egr3 function in a prostate cell model system is in progress, and the results of this analysis will help shed light on Egr3’s gene regulatory activities in prostate cancer and possible reasons for Egr3 expression pattern in prostate cancer." (PMID 23342084, 2013). "We are the first to describe the over-expression of Egr3 mRNA and protein in prostate cancer." (PMID 23342084, 2013). "Demographical information of 97 patients used for the analysis of Egr3 in relapse and non-relapse prostate cancer." (PMID 23342084, 2013). "Until now, Egr3 expression has not been examined in prostate cancer even though these two transcription factors are regulated by many of the same stimuli and bind the same DNA response element." (PMID 23342084, 2013). "We then focused on inflammation mediators IL6 and IL8 because of their known role in prostate cancer and their distinct expression pattern in relapse and non-relapse tumors that correlates with that of Egr3." (PMID 23342084, 2013). "The nature of Egr3 actions in prostate cancer is not yet clear; however some insight into its function can be gained through analysis of the genes whose expression correlates with it." (PMID 23342084, 2013). "Egr1 and Egr3 bind to similar sequence motifs on promoters and it is therefore unsurprising that they share a set of target genes such as IL6 and IL8, which we have now validated as direct targets for Egr3 in prostate cancer cells." (PMID 23342084, 2013). "This expression pattern: low Egr3 mRNA in normal prostate versus high expression in cancer, and distinction between relapse and non-relapse, was confirmed with the independent prostate cancer gene expression dataset from the University of Pittsburg." (PMID 23342084, 2013). "Analysis of median expression values also reveals a significant difference in Egr3 expression between normal prostate and prostate cancer samples (data not shown)." (PMID 23342084, 2013). "The γj tumor value for Egr3 is therefore both large magnitude (highly negative) and statistically significant, indicating that Egr3 is a candidate prognostic marker of poor outcome prostate cancer." (PMID 23342084, 2013).
prostate carcinoma (continued). "Through multiple linear regression analysis of Egr3 expression in specific cell types (tumor, stroma, BPH) we were also able to show that Egr3 mRNA is up-regulated in prostate cancer of men with less aggressive disease (non-relapse) but not in men who will eventually go on to relapse." (PMID 23342084, 2013).
hepatocellular carcinoma (8 papers, 2018 to 2025). A malignant tumor that arises from hepatocytes. "A distinct mechanism was also reported in hepatocellular carcinoma, where EGR3 promoted Fas ligand expression to drive apoptosis." (PMID 40649712, 2025). "EGR3 is also defined as a tumor suppressor, which inhibits cell proliferation and induces apoptosis in hepatocellular carcinoma in vitro." (PMID 34178038, 2021). "EGR3 is frequently declined in hepatocellular carcinoma tissues, retarded cell proliferation, and induced apoptosis in vitro." (PMID 34178038, 2021). "Early growth response 3 (EGR3), as a novel zinc finger transcription factor, is a newly discovered tumor suppressor gene, which can inhibit the growth of hepatocellular carcinoma, gastric cancer, and other cancer cells by up-regulation of Fas ligand." (PMID 32075046, 2020). "EGR3 is downregulated by microRNA 718, and EGR3 expression is significantly reduced in various hepatocellular carcinoma cell lines and tissues." (PMID 32612655, 2020). "MiR-718 was identified to have high likelihood for regulation of EGR3 and recently was confirmed to directly regulate EGR3 in hepatic carcinoma cell lines." (PMID 30308012, 2018).
gastric cancer (7 papers, 2020 to 2025). A primary or metastatic malignant neoplasm involving the stomach. "A study in gastric cancer also reported that decreased EGR3 expression is associated with poor prognosis, further confirming its suppressive potential in some tumor types." (PMID 40649712, 2025). "Although EGR3 has been implicated in breast and gastric cancers, its role in GBM remains unresolved." (PMID 40649712, 2025). "EGR3 expression has been shown to be significantly lower in gastric cancer tissues than in matched nontumor tissues, and patients with lower EGR3 expression show poorer prognosis than those with higher expression." (PMID 32612655, 2020).
bipolar disorder (6 papers, 2018 to 2024). A disorder of the brain that causes unusual shifts in mood, energy, activity levels and the ability to carry out day-to-day tasks. "Indeed, EGR genes, and EGR3 in particular, has been implicated in bipolar disorder, depression and Alzheimer’s disease." (PMID 29520222, 2018). "Recently, EGR3 was identified as a master regulator in a network of genes differentially expressed in the postmortem brains of bipolar disorder patients, compared with controls, in two independent cohorts." (PMID 29867393, 2018). "Additionally, a genetic link between EGR2 and EGR3 and bipolar disorder was recently identified." (PMID 39518903, 2024).
epilepsy (5 papers, 2010 to 2025). A brain disorder characterized by episodes of abnormally increased neuronal discharge resulting in transient episodes of sensory or motor neurological dysfunction, or psychic dysfunction. "Through the transcriptome analysis of the gene expression in hippocampus, Egr3, Nrg, Arc, and Ptgs2, closely related to epilepsy, had been proved to be downregulated by application of Dingxian pill." (PMID 31011358, 2019). "The results indicated that there are 57 differentially expressed genes in the intervention group and the control group (more than 2 times the expression level), some of which are closely related to epilepsy such as Egr3, Nrg1, Arc, and cox-2." (PMID 31011358, 2019). "For instance, Egr3 plays a role in 5 of the 6 categories: synaptic plasticity, epilepsy, transcription factors, proliferation, and neurogenesis." (PMID 31455240, 2019). "The Dingxian pills might interfere with epilepsy as well as cognitive dysfunction through Egr3-GABRA4 signal, NRG1-ErbB4 signal, and ERK-Arc pathway." (PMID 31011358, 2019). "In addition, the significant effect of Dingxian pill may be via mediating the Egr3-GABRA4, NRG1-ErbB4, MAPK-ERK-Arc, and cox-2-Pgp signal-pathways, which were associated with epilepsy." (PMID 31011358, 2019). "In developing neurons and epilepsy, BDNF is the endogenous signal that induces EGR3 expression via a PKC/MAPK-dependent pathway, and then EGR3 up-regulates the expression of GABRA4 by binding its promoter." (PMID 20156358, 2010).
glioblastoma (5 papers, 2020 to 2025). The most malignant astrocytic tumor (WHO grade IV). "EGR1 and EGR3 have been linked to glioblastoma stemness and tumour progression, and this study aimed to investigate their spatial expression and prognostic value in gliomas." (PMID 32518380, 2020). "Despite accumulating evidence implicating EGR3 in glioblastoma, its functional role remains unresolved, with previous studies reporting contradictory effects on tumor cell proliferation and progression." (PMID 40649712, 2025). "Our findings indicate that EGR3 promotes glioblastoma GBM cell growth, accompanied by increased expression of two oncogenic regulators, MYC and CDK1." (PMID 40649712, 2025). "Another study indicated that inhibiting TTN‐AS1 expression could accelerate apoptosis of glioblastoma cells and suppress its malignant biological behaviors, like proliferation, migration, and invasion via the miR‐320b/EGR3/PKP2 axis." (PMID 37528740, 2023). "Overall 207 gliomas including 190 glioblastomas were EGR1/EGR3 immunostained and quantified." (PMID 32518380, 2020).
leukemia (5 papers, 2017 to 2025). A malignant (clonal) hematologic disorder, involving hematopoietic stem cells and characterized by the presence of primitive or atypical myeloid or lymphoid cells in the bone marrow and the blood. "In leukemia, EGR3 expression was shown to be elevated at relapse and associated with immune and lineage differentiation pathways." (PMID 40649712, 2025). "Surprisingly, re-analysis of the Leukemia MILE study data involving 2096 patient samples using the online database BloodSpot revealed B cell malignancies to be characterized by a decreased EGR3 gene expression in comparison to healthy bone marrow (BM)." (PMID 37100882, 2023). "Since highly-expressed genes were usually regarded as having biological importance, we highlighted Maff and Egr3 as they were among the most highly expressed and their functional roles in HSCs under leukemia were less known." (PMID 28984203, 2017). "As known in previous researches, Maff and Egr3 are two important genes having opposite functions on cell cycle; however, they are both highly expressed in HSCs under leukemia." (PMID 28984203, 2017). "However, we also discovered that both Maff and Egr3 were highly expressed in hematopoietic stem cells (HSCs) under leukemia (especially at the late stage, i.e. ≥ day 14), in which the cell cycles of most HSCs were heavily suppressed." (PMID 28984203, 2017). "Therefore, the molecular mechanisms of how Maff and Egr3 act on cell cycle and why the two functionally-opposite genes are both highly expressed under leukemia, remain to be revealed." (PMID 28984203, 2017). "Furthermore, the relativity of Maff/Egr3 functions for HSC cell cycle can only be screened with a non-irradiated (i.e. un-manipulated) leukemia model, as intact HSCs without overt damages (e.g. immune system destruction) can be measured during leukemia progression." (PMID 28984203, 2017).
depression (4 papers, 2018 to 2024). "We have previously shown that Egr3 is required for stress-responsive behavior, memory, and hippocampal long-term depression in mice." (PMID 35941129, 2022).
melanoma (4 papers, 2021 to 2024). A malignant, usually aggressive tumor composed of atypical, neoplastic melanocytes. "We compared the overlap of DEGs between EGR3‐overexpressing melanoma cells and the gene expression profiles associated with differentiation in Schwann cells and melanocytes." (PMID 38973154, 2024). "As a tumor suppressor gene, EGR3 expression in melanoma tissue is associated with longer patient survival." (PMID 38973154, 2024). "The up‐regulation of COL1A1 and MPZ caused by EGR3 overexpression was validated in both A375 and B16‐F10 melanoma cell lines." (PMID 38973154, 2024). "Specifically, high expression of 4 key CRGs (ABCC2, CA14, LDHB, PSEN2) was significantly correlated with poor prognosis in melanoma patients (HR>1, P<0.05), while low expression of 2 key CRGs (EGR3, FBXW7) was significantly associated with poor prognosis (HR<1, P<0.05)." (PMID 39213172, 2024). "By machine learning algorithms, we identified 6 key CRGs (ABCC2, CA14, EGR3, FBXW7, LDHB, and PSEN2) closely associated with melanoma." (PMID 39213172, 2024). "In vitro, EGR3 induces melanoma cells to differentiate into Schwann cell‐like cells, leading to reduced migration, proliferation, and melanin secretion capability." (PMID 38973154, 2024). "This study first found EGR3 is downregulated in melanoma, and its low expression significantly impairs survival prognosis in melanoma patients." (PMID 39213172, 2024). "Collectively, these findings illustrate that recombinant mRNA vaccine triggers a Schwann cell‐like differentiation in melanoma cells via the EGR3 gene and bolster immune infiltration through the CD86 gene, ultimately resulting in effective tumor control." (PMID 38973154, 2024). "Due to the potential anti‐proliferative and differentiating capabilities of EGR3, we further developed a recombinant mRNA vaccine for melanoma treatment." (PMID 38973154, 2024). "Further analysis reveals that at the injection site (within the white dashed lines), SOX10‐positive melanoma cells successfully express EGR3." (PMID 38973154, 2024). "After EGR3 overexpression in melanoma cells, cell cycle arrest was observed in the G1 phase, accompanied by decreased levels of TYR expression and enzyme activity within the cells, resulting in reduced melanin production." (PMID 38973154, 2024). "Survival analysis showed a positive correlation between EGR3 and survival rates in melanoma cases, and patients with high EGR3 expression had significantly better survival rates than those with low expression." (PMID 38973154, 2024). "A positive correlation between the expressions of COL1A1 and MPZ with EGR3 expression in melanoma patients was also observed." (PMID 38973154, 2024). "Meanwhile, in vivo experiments demonstrate that EGR3 delays melanoma growth." (PMID 38973154, 2024). "Egr2 and Egr3 can induce the expression of Nab2 in melanoma cells." (PMID 38666929, 2024). "Transcriptome sequencing of EGR3‐expressing A375 melanoma cells revealed significant up‐regulation of multiple genes associated with the extracellular matrix (ECM), such as COL1A1, COL5A3, and FN1, thereby confirming the regulatory role of EGR3 in the remodeling of the extracellular space." (PMID 38973154, 2024). "Interestingly, TNF-α signalling via the NF-κB pathway was significantly downregulated with a reduction ranging from 7- to 40-fold in expression of some of its prooncogenic target genes (e.g., JUNB, FOS, DUSP1) and melanoma-related genes (e.g., EGR3, NR4A3, CCN1)." (PMID 34497073, 2021). "Compared to normal skin tissues, 4 key CRGs (ABCC2, CA14, LDHB, PSEN2) were significantly upregulated while 2 key CRGs (EGR3, FBXW7) were significantly downregulated in melanoma tissues." (PMID 39213172, 2024). "Among them, 4 key CRGs (ABCC2, CA14, LDHB, PSEN2) were significantly upregulated and 2 key CRGs (EGR3, FBXW7) were significantly downregulated in melanoma tissues." (PMID 39213172, 2024).
melanoma (continued). "Finally, by comparing the feature genes identified by the three machine learning approaches, six common key CRGs were identified as melanoma-related key CRGs, including ABCC2, CA14, EGR3, FBXW7, LDHB, and PSEN2." (PMID 39213172, 2024). "As we could not screen for stable overexpression of EGR3 in melanoma cell lines, the adenovirus vector expressing EGR3 was constructed for intratumoral injection of B16‐F10 melanoma in mice." (PMID 38973154, 2024). "However, further analysis of the 80 melanomas showed a negative correlation between T‐cells and EGR3 levels." (PMID 38973154, 2024).